C3 (complement C3)
Diseases named in the same sentence as C3 in open-access papers (continued):
Sharing a sentence is not in itself a finding about the gene and the disease.
tumor (continued). "In human tumors, six types of immune infiltrate were established that ranges from tumor-promotion to tumor-suppression, including C1 (wound healing), C2 (INF-γ dominant), C3 (inflammatory), C4 (lymphocyte depleted), C5 (immunologically quiet), and C6 (TGF-β dominant)." (PMID 34881236, 2021). "C3, FN1, and C3AR1 are overexpressed in multiple tumor cell lines." (PMID 34688260, 2021). "Taken together, these data indicate that overexpression of C3 confers CRC cells resistance to oxaliplatin treatment, The resistance mechanism may likely involve a reprogramming of the tumor immune microenvironment and oncogenic signaling." (PMID 34722636, 2021). "We evaluated stromal, tumoral and overall (i.e. combined C3 expression in both tumour cells and stroma) C3 expression status and dichotomized it as negative or positive based on staining intensity." (PMID 33658651, 2021). "Interestingly, the use of C3 inhibitor abrogated the immunosuppressive response of intra-tumor neutrophils, suggesting that complement inhibition could be a promising therapeutic strategy for ovarian cancer in which suppressive neutrophils impaired anti-tumor immunity response." (PMID 34572075, 2021). "In addition, C3, CR4, and C5aR1 expression was positively related to the tumor purity and infiltration levels of multiple immune cells in stomach adenocarcinoma (STAD)." (PMID 33614473, 2020). "As thrombin can also cleave C5 in the absence of C3, we evaluated C5 cleavage by immunohistochemical analysis of C5b-9 deposition in tumor tissues, which indirectly reflects the cleavage of C5." (PMID 28106852, 2017). "Tumor invasive depth (P = 0.561) and pathological stage (P = 0.542) were not correlated to preoperative C3 depletion." (PMID 29062836, 2017). "A strong signal for C1q was detected in all tumour specimens examined, while other C components were either absent (C4) or mildly expressed (C1s and C3) suggesting that C1q deposition did not result in the activation of the classical pathway." (PMID 26831747, 2016). "Complement C3 is one type of globulin that has enzymatic activity and is able to kill tumor cells independently in nonspecific immunity and assist antibodies and immune cells to kill the cancer cells." (PMID 24137307, 2013). "Here, we synthesise advances in intracellular and extracellular complement, with emphasis on complement component 3 (C3) and receptors (C3aR1, C5aR1/CD88, C5aR2/C5L2), highlighting how these pathways shape T-cell metabolism, exhaustion programmes and inflammatory tone within tumours." (PMID 41719156, 2026). "In addition, COTI-2-treated mice showed significantly decreased expression of Ki-67 and increased expression of Cleaved C3 in the xenograft tumor sections, indicating that COTI-2 could inhibit tumor proliferation and induce apoptosis of BCa in vivo." (PMID 39906622, 2025). "Furthermore, many studies have shown that in the absence of C3-C3aR or C5a-C5aR signalling, tumour growth in knockout mice is impaired compared to wild type (WT) mice, which complicates the interpretation of the results upon addition of radiotherapy." (PMID 39765018, 2025). "Beside complement regulators and receptors, components normally produced in the liver, as C1q, C1r, C1s, C3 and C5 are locally synthesized and deposited in different tumor types and in the stroma regardless of complement activation, being predominantly tumorigenic in the majority of cancer types." (PMID 40370471, 2025). "The reversal of tumor suppression caused by the absence of complement C3, resulting from the immune exhaustion of CD4+ T cells, provides evidence that tumors can drive immune evasion through C3/C5-dependent pathways." (PMID 39958348, 2025). "In contrast, other reports found that mice lacking C3 or C5aR showed decreased tumor growth." (PMID 37296948, 2023).
tumor (continued). "Furthermore, complement inhibition at the level of C3 (with a CR2-Crry fusion protein) in combination with radiation has been demonstrated to enhance the numbers of macrophages with an M1-like phenotype (F4/80+, CD11c+, CD206-) in lymphoma tumor models." (PMID 36249052, 2022). "However, the association between C3, C5, C3AR1, and C5AR1 expression and tumor infiltration of MDSCs and TAMs was not statistically significant and, in most cases, an inverse association was found." (PMID 34439277, 2021). "Given the involvement of many of these genes (such as C3, CD74, HLA-DR, STRA6, IGFBP4 and PIGR) in immune-mediated processes, it is tempting to speculate that their up-regulation indicates immune-mediated tumour control that is lost in malignant tumours." (PMID 32218455, 2020). "Furthermore, complement C3, C3a, C4, C4a, and C7 have been identified as biomarkers in HCC diagnosis while C7 and CFH are recognized for their critical roles in mediating stemness of tumor-initiating cells." (PMID 33718121, 2020). "Another report suggests that in colorectal cancer, only the C5a/C5aR1 axis and not C3, could play an important role in the modulation of tumor immunity, by recruiting MDSC and promoting tumorigenesis." (PMID 33113844, 2020). "However, C3 did not mediate cancer cell entry into the cerebrospinal fluid but other determinants were required for full tumor cell colonization." (PMID 31001273, 2019). "The levels of four essential proteins, including complement C3 and apolipoprotein C‐III in HCC, galectin‐3‐binding protein in CCA, and 72 kDa inositol polyphosphate 5‐phosphatase in cHCC‐CCA, were highly correlated with tumor stage, tumor grade, recurrence‐free survival, and overall survival." (PMID 31136099, 2019). "To test this hypothesis, we performed survival studies using tumor-bearing WT hosts or host mice lacking complement component C3 (C3-/-)." (PMID 25054064, 2014). "Furthermore, in 50% of tumor biopsies, C3 staining was not detectable in MelA+ cells." (PMID 35669782, 2022). "In the present study, we demonstrated increased expression of C3 in animals treated with anti-C1-INH, compared to control tumor tissue, whereas C5 was not significantly altered." (PMID 36717781, 2023). "While mRNA levels of C3, AKR1C3, GAL3ST1 were not completely correlated with tumor pathological grades and stages." (PMID 37035174, 2023). "A selection of the proteins from this panel are of high abundance in plasma (i.e., C3 and SERPINA1), while others are not (i.e., PF4 and ECM1), and so reflect the contributions of localized changes due to tumor presence and anti-tumor immunity." (PMID 35008327, 2021). "After adjustment for tumor purity, DHX37 in LIHC and LUAD showed negative correlations with C3 and other complement regulators but not significantly correlated with C5." (PMID 33490290, 2020). "In line with TCGA data demonstrating higher levels of C3 in GBM as compared with nontumor brain tissue, we found the vast majority of C3 present within the tumor core, with virtually no detectable stain in the tumor-adjacent healthy brain tissue." (PMID 39172519, 2024). "Therefore, our correlation analysis does not support the role of C3, C5, C3AR1, and C5AR1 in regulating tumor infiltration of TAMs and MDSCs and warrants experimental clarification." (PMID 34439277, 2021). "However, C3 levels between HCC and matched non-tumor liver tissues were not significantly different." (PMID 26760961, 2016). "Although effect of humoral immunity to tumor is not as important as that of cellular immune responses against tumor, IgM and IgG1 (IgG3) which might be in Gl-BSP-treated serum could mediate cytolytic activity with the help of component C3." (PMID 22811667, 2012).
cancer (207 papers, 2007 to 2026). A tumor composed of atypical neoplastic, often pleomorphic cells that invade other tissues. "Pack-years, family history of cancer, the levels of fibrinogen and serum C3 were independently associated with LC in patients with CPFE." (PMID 36769748, 2023). "Since the iTAAs and complement (C) are associated with cancer therapy Immunofluorescence (IF) was applied to evaluate the expression of the iTAAs and C3, C5, C9." (PMID 37336938, 2023). "A pan cancer multiomics analysis showed that the expression of C3/C5/C3AR1/C5AR1 is associated with the immune evasion signature, indicating the possible immune modulating role of complement proteins in HCC." (PMID 36341431, 2022). "While subtle tissue-specific differences in S1-associated cytokines and chemokines were seen across cancer types, our data showed that C3 is specifically and consistently upregulated by CD34high populations in multiple mouse models and human datasets." (PMID 32433953, 2020). "Moreover, dysregulation of the complement pathway, particularly increased C3 expression, was associated with poor clinical outcomes in various cancer types." (PMID 39964754, 2025). "Finally, using different The Cancer Genome Atlas (TCGA) datasets, we also demonstrated that in some cancer types, high C3 expression is associated with shorter progression-free survival." (PMID 32433953, 2020). "The complement molecules C3 and C4 have been previously associated with cancer progression and activation of PI3K signaling, whereas C5a is suspected to inhibit CD8 lymphocytes and natural killer (NK) cells, a subset of immune cells involved in the immune response towards tumors." (PMID 26485003, 2015). "Thus, C3 could serve a similar function in APC-related cancers by maintaining the association of metastatic cells in transit." (PMID 37489330, 2023). "Upregulation of C3 produced by cancer cells themselves has been reported to promote leptomeningeal metastasis by disrupting the integrity of the blood-cerebrospinal fluid barrier, allowing cancer cells to access mitogens and nutrients at the metastatic site." (PMID 40717170, 2025). "Addition of recombinant C3 at physiological concentrations rescued the decreased proliferation induced by C3 knockdown, supporting the concept that the C3 autocrine loop fuels cancer cell proliferation." (PMID 39964754, 2025). "In this way, the C3 enzyme was able to reach Rho proteins as intracellular drug targets to alter the morphology of cancer cells, expanding the evolutionary optimized features of C3 toxins for potential biomedical applications." (PMID 40480996, 2025). "Here, T regulatory cell (Treg) numbers were significantly increased after C3 deletion and suppressed anti-cancer immune responses." (PMID 39765018, 2025). "The dual-modified C3 enzyme was transformed beyond its native function, now enabling its uptake into the cytosol of cancer cells, where it remodeled the cytoskeleton, as well as fluorescence labelling for cell studies." (PMID 40480996, 2025). "Upregulation of complement component 3 (C3) has been identified as a critical mechanism through which cancer cells activate the C3a receptor in the choroid plexus, thereby disrupting the blood-CSF barrier." (PMID 40100294, 2025). "Regarding immune surveillance, the C3 protein was found to play a crucial role in helping the immune system identify cancer cells by regulating the membrane attack complex and several other processes." (PMID 40565234, 2025). "To determine the possible contributions of C1r and C3 to cancer, we investigated the alteration frequency of C1R gene using the cBioPortal database." (PMID 39254172, 2024). "In a paper reviewing expression of complement in various cancers most cancers over-expressed C3 but neutrally-expressed C5, and the most over expressed gene was CD59, suggesting efficient protection of malignant cells from complement-mediated killing." (PMID 37034706, 2023).
cancer (continued). "On the other hand, C3 and C5 have been suggested as targets for immunotherapy and as follow-up markers in pan-cancer scenarios." (PMID 37628784, 2023). "While C3 is generally known to promote cancer cell growth, several studies have demonstrated a contradictory role for C3 and observed anti-cancer effects." (PMID 37998326, 2023). "The Malmö Diet and Cancer cohort study found that in the general population, complement C3 was related to the incidence of first hospitalization of CKD." (PMID 36973754, 2023). "C3 has been found to promote neutrophil recruitment and the formation of neutrophil extracellular traps (NETs), which promote cancer cell metastasis to the lung." (PMID 37260987, 2023). "Many genes that were significantly upregulated in the RDEB inflammatory fibroblast subset, e.g., Il11, Lif, Vegf, Saa3, Tnc, and C3, are also the signature genes of iCAFs identified in many cancers." (PMID 37809094, 2023). "In cancers including HCC, release of complement mediators such as C2 and C3 has been linked to macrophage polarisation and TIL functional reprogramming, raising questions as to their potential role as a therapeutic target for cancer immunotherapy." (PMID 37274775, 2023). "The complement system has several proteins, C3 being the most abundant, and many studies have shown its role in cancer pathways." (PMID 37628784, 2023). "The upregulation of C3 was also demonstrated in several types of cancer and in different liquid biopsies." (PMID 37371512, 2023). "The complement C3 is a crucial activator of phagocytosis, it was reported to regulate cancer metastasis." (PMID 37287069, 2023). "The stable C3-expressing cancer cells consisted of a mixture of transfected cells with differential C3 expression due to the differential positioning of C3 in the genome." (PMID 35237583, 2022). "To optimize the FRET efficiency in cancer cells for drug screening, we selected single-cell clones of C3 expression from the bulk population." (PMID 35237583, 2022). "C3, the key complement component, is strongly expressed in all cancer types together with the components of the classical pathway." (PMID 35669782, 2022). "To confirm a role for C3 expressed in the cancer cells, we silenced expression of C3 in CMT cells using shRNA." (PMID 36686777, 2022). "To evaluate the production and secretion of the complement C3a by human pancreatic-derived cancer cells, we measured C3a in the supernatant of PANC-1 and MIAPaCa-2 by ELISA." (PMID 35937458, 2022). "Based on these findings, C3, activated in cancer cells, appears to be directly involved in the regulation of cancer cell survival." (PMID 35860237, 2022). "Cancer cells of BC‐LM and LC‐LM also disrupt the blood–CSF barrier by deriving C3 to activate the C3a receptor in the choroid plexus epithelium to allow plasma amphiregulin and other mitogens entering the CSF, which also promotes cancer cells growth in CSF." (PMID 35678121, 2022). "The efficacy of C3 and C4 has been demonstrated to induce apoptosis (in cancer cells) and regulate exosome secretion (in neurons)." (PMID 35406141, 2022). "Here, we demonstrate that C3 is a key gene associated with FOLFOX chemotherapy resistance and cancer recurrence risk." (PMID 34722636, 2021). "C3 is found to promote neutrophil recruitment and the formation of neutrophil extracellular traps (NETs), which facilitate cancer cell metastasis to the lungs." (PMID 34707103, 2021). "We found that C3, C5, C3AR1, and C5AR1 were frequently mutated (9~41%) in the studied cancer cohorts." (PMID 34439277, 2021). "We conducted a gene pathway activity and interaction network analysis to identify the effect of the complement component genes C3, C5, C3AR1, and C5AR1 on 10 major functional and signaling pathways associated with human cancer." (PMID 34439277, 2021).
cancer (continued). "Among the three cell types promoting T-cell exclusion, MDSCs and the M2 subtype of TAMs are negatively associated with the expression levels of C3, C5, C5AR1, and C3AR1, while only C3 expression shows a positive association with cancer-associated fibroblasts." (PMID 34439277, 2021). "Univariable logistic regression analysis indicated that old age, comorbidity of malignant tumor, neutrophilia, lymphocytopenia, increased CRP levels, lower CD4+ T cell count, and decreased C3 levels were associated with death." (PMID 32746940, 2020). "The cathepsins, for example, are a family of serine proteases that are upregulated and secreted by many different types of cancer, and cathepsin L can cleave C3 into C3a and C3b." (PMID 33167384, 2020). "In the colon, complement component 3 (C3) activation is a major contributor to inflammation and malignancies." (PMID 32817263, 2020). "Several inflammatory cytokines induce parenchymal cells to produce complement proteins, and the transcription factor twists basic helix-loop-helix transcription factor 1 (TWIST1) has been identified as a key regulator of the expression of C3 by cancer cells." (PMID 33167384, 2020). "Recently, C3 (−log10P‐adj = 24.08, log2FC = 1.84) from CSF cancer cells has been proved necessary for cancer growth within the leptomeningeal space." (PMID 33377642, 2020). "Leptomeningeal metastatic cells secrete complement C3 which has been proven to promote cancer growth in cerebrospinal fluid." (PMID 33708358, 2020). "This study is in line with previous observations of an abnormal expression of complement proteins in different type of cancer, especially C1 complex, C3, C4, C5, C3aR, C5aR1, FB, FH, FI, CD46, CD55, CD59." (PMID 33113844, 2020). "The aberrant expression of C3 from cancer cells indicates the relapse of the leptomeninges, with blocking of C3 signal found to effectively inhibit leptomeningeal metastasis." (PMID 33193896, 2020). "In ovarian cancer cells an autocrine loop in which expression of C3 by the cancer cells results in production of C3a which signals through the C3aR to promote growth." (PMID 31134065, 2019). "In combination, these changes suggest a role for C3 in regulating cancer cell aggressiveness through regulation of mitotic/cell division machinery function." (PMID 29464047, 2018). "The concentrations of the complement systems’ components, in particular C3, determine the patients’ ability to fight cancer by CDC." (PMID 27905089, 2016). "Since ELISA test did not confirm significant differences in the expression of complement component C3, further study will involve a quantitative approach to prove clinical utility of the other proteins from the proposed multi-peptide cancer signature." (PMID 27043541, 2016). "The results of our study should draw more attention to the possibility of use of complement-related proteins, especially C3, as new molecular cancer biomarkers." (PMID 27043541, 2016). "Finally, to study the activation of complement system in association with MUC1 expression, we evaluated the deposition of PTX3 and C3 in cancer tissue." (PMID 41533164, 2026). "Our study suggests this peptide + C3-liposome conjugation method may allow for an efficient delivery system that could be utilized in personalized cancer therapies." (PMID 40507796, 2025). "The significantly higher complement levels (C3 and C1q) in cancer patients may reflect an exaggerated immune response, which is consistent with reports of increased complement activation in both cancer and COVID‐19." (PMID 40129313, 2025). "Although each cancer can exhibit its unique cocktail of complement regulatory proteins, we show here that cells expressing C3 in the GBM microenvironment also upregulated several components of the classical pathway and downregulated early complement inhibitors." (PMID 39172519, 2024). "This suggests that C3 also plays a cancer-promoting role in ccRCC." (PMID 37260987, 2023).